IL6 (interleukin 6)
Diseases named in the same sentence as IL6 in open-access papers (continued):
Sharing a sentence is not in itself a finding about the gene and the disease.
Obesity (continued). "The asthma and obesity groups showed an increase in cytokine of IL-17A, IL-4, IL-6, TNF, IL-1β and IL-18 in the BALF compared with normal controls." (PMID 29160418, 2017). "When compared to the control group, T2DM seems to act synergistically with obesity to promote an increase in IL-6 levels." (PMID 28225860, 2017). "On the contrary, in the same study, the complete blockade of IL-6 (both classic and trans-signaling) exacerbates obesity/induced weight gain, liver steatosis, or insulin resistance." (PMID 28250574, 2017). "This is of clinical relevance in severe obesity as IL-6 is highly expressed both, in liver and adipose tissue, and successful weight loss as achieved by bariatric surgery almost eliminates this overproduction." (PMID 28758929, 2017). "Age-related changes in fat tissue inflammatory profiles resemble those in obesity, in which senescent stem cells and endothelial cells accumulate along with an increase in circulating pro-inflammatory cytokines, including TNFα and IL-6." (PMID 28241882, 2017). "The best-studied inflammatory players in obesity are TNFα and IL-6, but also include IL-17, CCL-2, and many others." (PMID 28233125, 2017). "We have demonstrated that in diet-induced obesity, the chronically high IL-6 levels lead to the development of hepatic IL-6 resistance." (PMID 28233125, 2017). "Interleukin (IL)‐6−/− mice develop mature onset obesity, whereas i.c.v. injection of IL‐6 decreases obesity in rodents." (PMID 29024103, 2017). "The results revealed that more than 70% of the patients suffering from NDs, depression, and obesity, had decreased expression of both IL-1β and IL-6 (P < 0.001)." (PMID 29736225, 2017). "Paradoxically, work from our laboratory and others have highlighted that complete ablation of IL-6 in mice can lead to deleterious metabolic consequences such as glucose intolerance, obesity and more importantly increased liver steatosis and damage." (PMID 28632778, 2017). "Many studies have shown that pro-inflammatory mediators including tumor necrosis factor-α (TNF-α), interleukin-1β (IL-1β) and interleukin-6 (IL-6) are increased during obesity and diabetes." (PMID 28282929, 2017). "The results demonstrated that obesity induced significantly higher expression levels of IL-6 and TNF-α in sera." (PMID 29354072, 2017). "Pro-inflammatory IL-6, a biomarker of obesity and T2D is a critical contributor to insulin resistance, and cardiovascular disease, including myocardial infarction and atherosclerosis." (PMID 29095915, 2017). "Cytokines, in particular TNFα, IL-1 and IL-6, act as potent stimulators of ROS production by the monocyte-macrophage lineage cells infiltrating adipose tissue in obesity through the activity of NADPH oxidase." (PMID 28582461, 2017). "It is becoming increasingly recognized that obesity results in a chronic low grade inflammation accompanied by increased production of cytokines such as IL-6." (PMID 28319140, 2017). "In obesity, insulin resistance develops as a consequence of metaflammation in which elevated circulating levels of pro-inflammatory cytokines such as TNFα and IL-6 negatively affect the insulin signaling cascade." (PMID 28233125, 2017). "The expression of IL-6 in central nervous system negatively correlates with the expansion of adipose tissue during obesity." (PMID 29163240, 2017). "Another major mechanism responsible for CRC is low grade inflammation seen in obesity with increased IL-1b, IL-6, TNF-a and NF-kB." (PMID 28819564, 2017). "Inflammatory cytokines, such as tumor necrosis factor-α (TNF-α) and interleukin-6 (IL-6), are individually considered as important contributors to endothelial dysfunction in obesity and type 2 diabetes (T2D)." (PMID 29095915, 2017). "IL-6-deficient mice showed decreased body composition and developed mature-onset obesity, which were partly reversed by IL-6 replacement treatment." (PMID 29213091, 2017).
Obesity (continued). "Collectively, our studies reveal that IL-6 action in T cells through classical IL-6 signalling promotes inflammation and insulin resistance early during obesity development, which can be compensated for by enhanced IL-6 trans-signalling at later stages." (PMID 28466852, 2017). "This is the first study to investigate whether IL6 methylation in a readily accessible tissue is associated with depression status, however methylation has been associated with a range of other conditions including Alzheimer’s dementia, prostate cancer and obesity." (PMID 29070016, 2017). "Obesity-induced pro-inflammatory cytokines and LPS polarize KC towards Mpro that in turn induce a vicious cycle of TNFα, IL-6, and IL-1β that further boosts and deteriorates liver functions." (PMID 28233125, 2017). "As a matter of fact, abundant fat tissue in obesity is linked to enhanced secretion of pro-inflammatory adipokines including TNF, leptin, IL-6 and IL-18, RBP-4, CCL2, CXCL5, lipocalin 2, and ANGPTL2." (PMID 27625607, 2016). "The overexpression of crucial pro-inflammatory cytokines, e.g., TNFα, IL-6 and MCP-1, which is associated with the state of obesity, is closely connected to insulin resistance as well as diabetes mellitus 2 or cardiovascular syndrome development." (PMID 27983705, 2016). "The inflammatory microenvironment created by excess adipose tissue has lately received increasing attention, and one of the key cytokines in the link between obesity and cancer is in fact IL-6." (PMID 27329584, 2016). "Specifically, visceral adipose tissue is an important source of circulating IL-6 in relation to obesity." (PMID 28025491, 2016). "Previous studies have showed that a low-grade inflammation characterized by increased circulating levels of proinflammatory cytokines in adipose tissue, such as IL-6 and Tnf, and chemokines is a common feature of obesity and diabetes." (PMID 26881249, 2016). "Patients with obesity often have elevated serum levels of proinflammatory molecules, such as IL-6, which induce a systemic chronic inflammatory state." (PMID 26884646, 2016). "The pro-inflammatory cytokines TNFα, IL-1β, and IL-6, considered as highly involved in obesity-related IR and the anti-inflammatory cytokines IL-4 and IL-10 displayed similar levels in CT, OIS, and OIR subjects." (PMID 27111539, 2016). "The secretion IL-6 is complex as evidence suggests that this cytokine can have both detrimental effects in obesity and yet positive effects on tissue homeostasis and potential to resolve inflammation." (PMID 26954359, 2016). "Low-grade lingering inflammation (e.g., increased levels of TNF-α and IL-6) and protein and lipid oxidation are commonly reported in individuals who have obesity." (PMID 27440160, 2016). "This suggests that adipose tissue is a source of the increased circulating IL-6 observed in obesity." (PMID 27642351, 2016). "Factors that are elevated in obesity, such as tumor necrosis factor α (TNFα) and interleukin 6 (IL6), increase the expression and secretion of MCP-1." (PMID 28030645, 2016). "Obesity is associated with increased expression of PTH, duodenal 5-HT, IL-6, AGEs and THF-α, as well as decreased expression of BMP, IGF, Activin/TGF-β, Wnt, brain 5-HT, estrogen and EPCs." (PMID 27746742, 2016). "Obesity also induces “smoldering” inflammation causing a permanently elevated level of cytokines (TNF alpha, IL-6, CRP) which promote tumurigenesis." (PMID 26951106, 2016). "Interlukin-6 (IL-6) is one of the most prominent inflammatory cytokines in obesity and diabetes research because its serum concentration positively correlates with increased fat mass." (PMID 26954359, 2016). "Obesity increases levels of inflammatory adipokines such as interleukin‐6 (IL‐6) and tumor necrosis factor‐alpha (TNF‐α), which induce insulin resistance." (PMID 26990883, 2016). "Most convincingly, blockade of IL-6 or osteopontin rescued obesity-induced melanoma growth into the bone marrow and normalized osteoclast activation." (PMID 27049717, 2016).
Obesity (continued). "Adipose IL-6 secretion is markedly increased in vivo in obesity, along with systemic elevation, especially in IR individuals." (PMID 27342408, 2016). "In humans, high levels of IL-6 are associated with glucose intolerance, T2DM, SAH, and especially obesity." (PMID 27408717, 2016). "Nowadays, obesity is considered chronic, low-grade inflammation, with excess production of IL-1β, Il-6 and TNF-α." (PMID 27097934, 2016). "Using a BMI of >30 as a cutoff, those with elevated IL-6 and obesity had the lowest FEV1, had more exacerbations, and were more likely to have features of metabolic syndrome." (PMID 27610226, 2016). "In the mouse models of obesity lavaged neutrophils and IL-6 were also increased with ozone exposure for both wild-type and obese mice, with a significantly greater increase in IL-6 for the obese mice." (PMID 27513854, 2016). "On the other hand, circulating plasma IL-6 levels are elevated in individuals with type II diabetes, obesity and insulin resistance." (PMID 28025491, 2016). "Considering obesity as a chronic inflammatory disease, we examined the levels of IL-6 both in obese and normal mice by ELISA." (PMID 27329259, 2016). "IL-6 is a potent inducer for hepatic synthesis of CRP and other acute phase proteins in obesity and therefore leads to increased risk of cardiovascular disease." (PMID 26909479, 2016). "In fact, obesity is associated with a hyperexpression of TNF-α and other adipokines (e.g., IL-6, leptin, adiponectin) and transforming growth factor-β, which leads to a chronic proinflammatory state." (PMID 27964760, 2016). "In obesity, macrophages infiltrate adipose tissue and begin to induce proinflammatory cytokines, such as IL-1β, TNFα, and IL-6, which contribute to insulin resistance." (PMID 27066503, 2016). "High-fat diet-induced obesity (DIO) is associated with fatty liver and elevated IL-6 circulating levels." (PMID 27333268, 2016). "IL-17A can induce expression of TNF-α, IL-6, and IL-1β cytokines, which are found with increased levels in obesity." (PMID 27070576, 2016). "This work certainly identifies serum IL-6 as an important biomarker in severe asthma and links it to obesity and metabolic syndrome." (PMID 27610226, 2016). "Recently, the Icelandic Sleep Apnea Cohort study interestingly revealed that OSA severity was an independent predictor of IL-6 and CRP levels, but interacted with obesity such that this association was found only in obese patients." (PMID 27684378, 2016). "Obesity is often described as a low-grade inflammatory state and consistent with this notion plasma IL-6 was increased, and TNFa (P = 0.14) and IL-10 (P = 0.08) tended to increase, in obese vs. lean mice." (PMID 27351281, 2016). "This is shown to be effective in eliminating obesity-related inflammation since significant reductions in levels of IL-6 were noted with intervention combining Vitamin D3 supplementation and weight-loss program." (PMID 27703587, 2016). "Alterations in the levels of adipokines including a decrease in adiponectin and increases in leptin and IL‐6 are primary links between obesity and systemic inflammation, as well as signs of progression of metabolic dysfunction." (PMID 26990883, 2016). "Obesity causes an abnormal expression of adipokines (e.g., tumor necrosis factor-α [TNF-α], interleukin-6 [IL-6], adiponectin, leptin), which leads to a proinflammatory status." (PMID 27964760, 2016). "The findings demonstrate that a transient early postnatal overweight induces early-onset (P21) obesity, accompanied by activation of pulmonary adipocytokine/insulin signaling and increased pulmonary expression of pro-asthmatic IL-6, IL-13, IL-17A and Tnf-α." (PMID 27087690, 2016). "It has been confirmed that concentrations of pro-inflammatory cytokines such as TNF-α, IL-6 and CRP are elevated in obese subjects and elevated TNF-α, IL-6 are associated with obesity related insulin resistance." (PMID 27409634, 2016).
Obesity (continued). "Fibrinogen is regulated by interleukin-6 (IL-6) in adipose tissue and adipose tissue IL-6 expression was shown to be positively correlated with obesity." (PMID 27594807, 2016). "For example, macrophages of obese individuals accumulate in adipose tissue, where they express pro-inflammatory cytokines such as TNFa, IL6, and INOS, and the gut microbiota can initiate the inflammation and insulin resistance associated with obesity." (PMID 26884067, 2016). "In conclusion, significant biomarkers of inflammation (TNFα, IL-6, hsCRP, and haptoglobin) and endothelial dysfunction (sICAM-1 and sVCAM-1) are present in young patients with diabetes, obesity, and dyslipidemia." (PMID 27459718, 2016). "It has also been proposed that IL-6 released from adipocytes stimulates hepatic synthesis of C-reactive protein (CRP) in obesity." (PMID 26942201, 2016). "Diet-induced obesity also increases Th17 cell number in mouse adipose tissue because adipose tissue dendritic cells secrete higher levels of IL-6, TGF-β, and IL-23 to promote Th17 cell generation." (PMID 27070576, 2016). "This skewing is thought to be due to a chronic inflammatory Th1/Th17 type milieu during obesity, with increased IL-6, TNF-α and IFN-γ." (PMID 27483441, 2016). "It is known that during processes such as obesity or atherosclerosis, there are increased levels of proinflammatory cytokines such as IL-6 and TNF-α, which are capable to activate NF-κB in different tissues." (PMID 26055507, 2015). "First, our data show the elevated adipose tissue expression of IL-6R and IL-6 in obese individuals and the changes correlate with clinical indicators of obesity including BMI and PBF." (PMID 26200663, 2015). "It has been widely shown that IL-6 expands the TH17 fraction in obesity while being concurrently induced by IL-17A itself." (PMID 26263971, 2015). "Actually, IL-6, MCP-1, resistin, and TNF-α are associated strongly with obesity-induced inflammation and obesity-related pathologies." (PMID 26248075, 2015). "There are two types of evidence indicating obesity as a chronic inflammatory illness: the release of proinflammatory cytokines such as TNFα, IL-6 and IL-1β from adipose tissues and infiltration of macrophages into the WAT." (PMID 26347815, 2015). "Adipose tissue release cytokines such as IL-6 and IL-1β in obesity that targets several tissues such as the heart, the pancreas, or the liver." (PMID 26568663, 2015). "Our data showing IL-6 perturbations in obesity extend and confirm the previous findings; while the data on the adipose tissue IL-6R changes in obesity add further information." (PMID 26200663, 2015). "Four common variants involved in inflammatory-adipokine triggering (IL6 rs2069845, LEPR rs1137100, NAMPT rs3801266, and AMD1 rs2796749) have recently been associated with obesity and related traits in Indian children." (PMID 26558825, 2015). "As observed in mice models of diet-induced obesity, TLR4 deficiency prevented the enhanced release of TNF-α and IL6 in our hypoxic mice." (PMID 25873766, 2015). "Such desensitization is likely occurring in situations of chronic elevation in IL-6 levels, such as occurs in human obesity." (PMID 25688211, 2015). "Adipose (fat) tissue plays a role in pro-inflammatory cytokine secretion; obesity is associated with an increased number of macrophages, which are responsible for most of the TNF-α and IL-6 cytokine production." (PMID 26340637, 2015). "The effect of obesity, of causing chronic low-grade inflammation with an elevation of inflammatory markers (such as CRP, TNF-α, and IL-6) that increase the risk of cardiovascular disease, is even more pronounced in PCOS." (PMID 26124830, 2015). "For example, IL-6 knockout mice develop obesity, elevated leptin, and altered glucose homeostasis with aging, suggesting that long-term IL-6 depletion can contribute to metabolic dysfunction." (PMID 26217222, 2015).
Obesity (continued). "IL-6 is a pleiotropic cytokine that induces either proinflammatory or antiinflammatory responses and is involved in a variety of conditions, such as obesity, arthritis, colitis, and sepsis." (PMID 26294848, 2015). "Interleukin-6 (IL-6) is released by mononuclear leucocytes and adipose tissue, with levels being elevated in obesity." (PMID 26124830, 2015). "As do humans, HFD-fed wild-type mice developed obesity, moderate steatosis and elevated IL-6 serum levels." (PMID 26035386, 2015). "Over the past decade, interleukin-6 (IL-6) has emerged as a highly versatile cytokine with important repercussions for the endocrine system, particularly in obesity and insulin resistance." (PMID 26035386, 2015). "Obesity is associated with elevations in insulin, free insulin-like growth factors (IGFs), and adipocyte-derived factors that include leptin, TNF-alpha, IL-6, and reductions in adiponectin." (PMID 25811460, 2015). "Several studies have shown that obesity is associated with elevated serum levels of a wide range of inflammatory markers including C-reactive protein (CRP), interleukin 6 (IL-6), interleukin 8 (IL-8), and monocyte chemoattractant protein 1 (MCP-1)." (PMID 25972622, 2015). "The second explanation is that the production of adipokines by fat tissue, such as IL-6 and tumor necrosis factor-α, enhances obesity-induced inflammation." (PMID 25889813, 2015). "It was separately reported by two different studies that plasma and adipose tissue levels of IL-6 correlated better than TNF-α with obesity and insulin resistance." (PMID 26200663, 2015). "Serum levels of interleukin-6, and haptoglobin were found to be strong predictors of complications in severe obesity by linear regression analysis." (PMID 27275205, 2015). "Interleukin-6 has been recently proposed to play a central role in the link between obesity, inflammation and coronary heart diseases." (PMID 27275205, 2015). "For IL-6 a similar pattern was observed however obesity appeared to dampen the impact of exercise on IL-6 mRNA in offspring of obese dams (CE 2.5±0.5 vs CS 0.87±0.2; FE 1.58±0.3 vs FS 0.87±0.1, P<0.05)." (PMID 25853572, 2015). "Most likely, any suppressive role that NO exerts on IL‐6 release in this study appears to occur independently of obesity or hyperglycemia." (PMID 26660551, 2015). "Chronically-elevated IL-6 has been described to be related to metabolic disorders such as obesity and IR." (PMID 26578976, 2015). "Biomarkers of obesity (leptin, adiponectin), diabetes (glucose, insulin), inflammation (C-reactive protein, Interleukin-6, surface tumor necrosis factor receptor (sTNFR) I & II) and oxidative stress (F2-isoprostanes) were measured in stored blood samples." (PMID 26380096, 2015). "We measured mRNA levels of genes encoding for several markers of inflammation related to obesity, including the chemokine MCP1 (Ccl2), proinflammatory cytokine IL6 (Il6) and TNFα (Tnf), and macrophage-specific marker F4/80 (Emr1) in adipose depots." (PMID 25745505, 2015). "Across all studies, l-ascorbic acid was associated with smoking status, alcohol intake, physical activity, and socioeconomic position alongside obesity, insulin, C-reactive protein, IL-6, and urate (where available)." (PMID 25527764, 2015). "Herein, we present the data showing that obesity enhances gene and protein expression of the IL-6R and IL-6 in the human subcutaneous adipose tissue which correlates positively with the local expression of several inflammatory markers." (PMID 26200663, 2015). "IL-6 strongly correlates with insulin resistance and type 2 diabetes and its plasma levels are increased in patients with obesity and type 2 diabetes." (PMID 26055507, 2015). "Obesity, specifically abdominal or visceral obesity, leads to high levels of pro-inflammatory adipokines including IL–6, IL–1β, leptin and TNF-alpha." (PMID 26437377, 2015).